HMOX1 (heme oxygenase 1)
Diseases named in the same sentence as HMOX1 in open-access papers (continued):
Sharing a sentence is not in itself a finding about the gene and the disease.
retinal detachment (1 paper, 2024). An eye emergency condition which may lead to blindness if left untreated. "In a retinal detachment model, NMN treatment has shown an increment in retinal NAD+ levels and upregulated SIRT1 and heme oxygenase-1 (HO-1)." (PMID 38397799, 2024).
Right ventricular dilatation (1 paper, 2019). Enlargement of the chamber of the right ventricle, which can be defined echocardiographically as a right ventricular to left ventricular ratio greater than 1:1. "In HO-1-deficient (Hmox1−/−) mice, hypoxia induced severe right ventricular dilatation and infarction." (PMID 31344980, 2019).
salmonellosis (1 paper, 2012). Infections with bacteria of the genus salmonella. "For example, iNOS-dependant induction of 8-nitroguanosine 3′,5′-cyclic monophosphate (8-nitro-cGMP) has been shown to induce heme oxygenase 1 (HO-1) which has both cytoprotective and antimicrobial effects in murine Salmonellosis." (PMID 22848212, 2012).
secondary progressive multiple sclerosis (1 paper, 2020). A multiple sclerosis with a clinical course characterized by a progressive accumulation of neurological disability, independent of relapses, following an initial relapsing-remitting (RR) phase. "Along with the expression of regulatory cytokine IL-10, HMOX-1 encoding for HO-1 was reduced in monocytic MDSCs of secondary progressive multiple sclerosis (MS) patients when compared to relapsing–remitting MS patients or healthy subjects." (PMID 32265903, 2020).
stress cardiomyopathy (1 paper, 2025). "Circulating IL-1β and IL-18 index inflammasome activity relevant to stress–lipid crosstalk; heme oxygenase-1 (HO-1) is upregulated in stress cardiomyopathy and reflects oxidative stress." (PMID 41156076, 2025).
uremia (1 paper, 2025). A clinical syndrome associated with the retention of renal waste products or uremic toxins in the blood. "Among them, HMOX1, SOD2, and NOS2 have become the key targets - which is consistent with their previous research that can protect renal tubules from oxidative damage, maintain mitochondrial antioxidant capacity, and regulate the oxidative-reductive imbalance associated with uremia." (PMID 41560720, 2025).
tumor (694 papers, 1999 to 2026). "Recent studies have demonstrated that tumor-associated myeloid cells, particularly hyperactivated macrophages, exhibit elevated expression of heme oxygenase-1 and play a key role in ALA metabolism." (PMID 41009470, 2025). "Heme oxygenase-1 (HO-1), an inducible enzyme involved in heme degradation, has been implicated in both hepatoprotection and tumor progression." (PMID 41157261, 2025). "For example, the increased levels of HMOX1 have been associated to tumor aggressiveness and presence of serine/threonine-protein kinase B-Raf (BRAF)V600E mutation." (PMID 40927570, 2025). "The SPP1+ macrophage cluster also expressed HMOX1, which has been shown to play a role in the immunosuppressive program of tumor-associated macrophages (TAM)." (PMID 40647416, 2025). "Fasting-induced tumor-infiltrating lymphocyte (TIL) recruitment mediated by heme oxygenase-1 (HO-1) was significantly associated with lower numbers of regulatory T cells (Treg) in the tumor clinic." (PMID 39595613, 2024). "Oncogenes in cancer cells or genetic mutations in the HMOX1 promotor, the gene encoding HO-1, can drive the constitutive expression of HO-1, leading to potent immunomodulating anti-tumor immune responses." (PMID 39273143, 2024). "It is worth mentioning that HMOX-1 has been associated to several functions that overall create a microenvironment that favors tumor growth." (PMID 38069002, 2023). "More importantly, it was observed that the inhibition of mTOR by pharmacological VC supplementation in vivo produces positive therapeutic responses in tumor growth, while HMOX1 deficiency rescues the inhibitory effect of pharmacological VC on tumor growth." (PMID 36787291, 2023). "On the other hand, the high level of this transcription factor and its target genes encoding cytoprotective proteins (such as HMOX1 encoding HO-1) can protect tumor cells against chemotherapy." (PMID 36771178, 2023). "The aim of our study was to explore the downstream effects of heme oxygenase‐1 (HO‐1), the rate‐limiting enzyme in the heme catabolism pathway, on the immune suppressive functions of human tumor‐associated BMDMs, found upregulated in our previous study." (PMID 36054818, 2022). "Heme oxygenase-1 (HMOX1) is an inducible intracellular enzyme to degrade heme, expressed in both malignant tumor cells and tumor-associated macrophages (TAMs)." (PMID 36033490, 2022). "Heme Oxygenase-1 total protein expression was also associated with advanced tumor stages, T status and with lymph node metastasis but an association with patient survival has not been found." (PMID 33440611, 2021). "Heme oxygenase-1 (HO-1) is induced and overexpressed in various types of cancer and is associated with features of tumor aggressiveness." (PMID 34199169, 2021). "Although, the expression of HO-1 is heavily influenced by the TME, there are instances where HO-1 can be constitutively expressed by tumor cells due to oncogenes driving the HMOX1 promoter or genetic mutations within the promoter itself." (PMID 33868304, 2021). "Heme oxygenase-1 (HO-1) is an antioxidant protein implicated in tumor progression, metastasis, and resistance to therapy." (PMID 34199777, 2021). "Heme Oxygenase-1 (HO-1) is a critical enzyme during heme metabolism and is associated with tumor resistance toward chemotherapy or radiotherapy-induced apoptosis." (PMID 32375828, 2020). "HOXA13 is linked to poor prognosis in many cancers and HMOX1 has a role in protecting tumor cells from apoptosis." (PMID 32550915, 2020). "While HMOX-1 expression is induced by oxidative stress in healthy cells to serve a beneficial and tumor-suppressive role, unregulated expression of HMOX-1 acquired by certain cancers is linked to increased cell-survival and proliferation." (PMID 31251786, 2019). "HMOX-1 influences tumor initiation and progression in part by alternating E-cadherin expression from tumor-associated macrophages." (PMID 31581661, 2019).
tumor (continued). "This gene was also of interest based on its overexpression in certain cancers and on the association of HMOX-1 activity with survival and proliferation of tumor cells." (PMID 31251786, 2019). "Expression of tumoural Hmox1, the gene encoding HO-1, was also detected at the point of tumour establishment (day 9 post inoculation) and was associated with the TAM population, where its expression correlated with FAP." (PMID 30054470, 2018). "Our group has shown that tumor-associated macrophages (TAMs) can inhibit immune-mediated tumor rejection in vivo through their expression of the heme-degrading enzyme heme oxygenase-1 (HO-1)." (PMID 29872437, 2018). "On the other hand, immunosuppression by FAP+ tumour associated macrophages is mediated by heme-oxygenase-1 (HO-1)." (PMID 28158223, 2017). "Heme oxygenase 1 (HO-1) is an important enzyme involved in angiogenesis and tumor metastasis and its activity have been associated to matrix metalloproteinases expression." (PMID 27834913, 2016). "Heme oxygenase 1 (HO-1) has been implicated in maintaining cellular homeostasis, but also in tumor angiogenesis." (PMID 23591596, 2013). "Notably, heme oxygenase-1 (HO-1), one of the three distinct isoforms belonging to the heme oxygenase (HO) family, has emerged as a pivotal component in Nrf2-mediated mechanisms underlying tumor resistance to anticancer therapies." (PMID 37759607, 2023). "In addition, T47Ds seem quite deficient in heme oxygenase 1 (HO‐1), a member of the heat shock protein family that has been shown to alleviate oxidative stress in tumor cells." (PMID 32737955, 2022). "Moreover, a previous study showed that high expression of HMOX-1 was associated with tumor aggressiveness and BRAFV600E expression in a subset of thyroid cancers." (PMID 35053476, 2022). "Moreover, HMOX1 signature was associated with T‐cell function in tumor environment." (PMID 37031459, 2023). "Further analysis identifies IPO9 as a core gene upregulated in OC, promoting tumor progression by inhibiting HMOX1‐dependent ferroptosis." (PMID 41584724, 2026). "Recently, HMOX1 has been revealed to play key roles in the process of ferroptosis and disease progression, especially in tumor development, which provides novel potential molecular targets for disease treatment." (PMID 39706989, 2025). "In particular, heme oxygenase 1 (HMOX1) has potent antioxidant and anti-apoptotic properties that boost tumor cell proliferation and treatment resistance." (PMID 40649369, 2025). "Targeting the Hmox1/iron/Kdm6b signaling pathway in FerroCAFs was shown to enhance anti-tumor immunity and suppress tumor growth in experimental models." (PMID 40649958, 2025). "The edited CYP1A1 enhanced the interaction with heme oxygenase-1 (HO-1) and mediated the nuclear translocation of HO-1 to confer resistance to oxidant stress, which promoted cell proliferation and tumor progression in NSCLC." (PMID 40175891, 2025). "It is now accepted that heme‐oxygenase 1 (HMOX1), a stress response gene, regulates tumour cell ferroptosis." (PMID 40495644, 2025). "Our research shows that SD can effectively induce ferroptosis by targeting key regulators such as HMOX1, thereby inhibiting tumor growth and promoting cell death." (PMID 40383858, 2025). "Elevated GCLC and HMOX1 correlate with poor prognosis, tumor progression, and treatment resistance, including CRPC." (PMID 39936983, 2025). "These macrophages support the maintenance of an immunologically ‘cold’ tumor microenvironment (TME) through their expression of the enzyme heme oxygenase-1 (HO-1)." (PMID 40768602, 2025). "This suggests a potential correlation between SPP1/HMOX1 expression and the degree of tumour malignancy." (PMID 40495644, 2025). "These macrophages express high levels of the enzyme heme oxygenase-1 (HMOX1), which contributes to tumor growth and correlates with poor survival outcomes." (PMID 40330466, 2025).
tumor (continued). "More significantly, proteomic and genomic investigations uncover that the CO-induced activation of AKT signaling pathway, NRF-2 phosphorylation and HMOX-1 overexpression induce mitochondrial dysfunction to boost anti-tumor consequences." (PMID 39014402, 2024). "In summary, there are diverse pathways through which HMOX1 expression can be elevated, and increased HMOX1 levels contribute to cancer progression through both tumor cell intrinsic mechanisms and modulation of the TME." (PMID 39850572, 2024). "This complex of nanoparticles selectively accumulates in tumor sites, triggering ferroptosis by inducing ROS production and regulating the expression of KEAP1, NRF2, and HMOX1, which in turn elevates the labile iron pool in 4T1 tumor-bearing BALB/c model mice." (PMID 38962305, 2024). "To eliminate confounding effects of stable HMOX1 KO on tumor progression, we established Hmox1-inducible knockdown cell lines based on a doxycycline-inducible shRNA expression system." (PMID 39621310, 2024). "An increase in NRF2 content increases the expression of heme oxygenase-1 (HO-1) and BTB domain and CNC homology 1 (BACH1) and the related factors associated with cancer tumor invasion and metastasis." (PMID 38385979, 2024). "Some studies have also reported that HMOX1, SST, PLA2G2A, KRT4 and COL3A1 are associated with tumor progression and prognosis." (PMID 38461430, 2024). "We found that the induction of Hmox1 knockdown enhanced RT efficacy, leading to decreased tumor volumes in the B16, MC38, and 4T1 models." (PMID 39621310, 2024). "Heme Oxygenase-1 (HO1) acts as an immunotherapeutic molecule in tumor myeloid cells, in addition to promoting chemoresistance in cancer cells." (PMID 39201574, 2024). "Under RT, HMOX1 knockdown resulted not only in delayed tumor growth but also elevated intratumoral IFN-I and ISG expression." (PMID 39621310, 2024). "In the context of skin sensitization, HMOX1 has been shown to be upregulated in response to contact sensitizers in dendritic cells and the THP-1 cell line, suggesting its involvement in the cellular response to sensitizing agents." (PMID 39727897, 2024). "TalaA promotes ferroptosis by increasing intracellular reactive oxygen species and up-regulating transferrin and heme oxygenase 1, thereby inhibiting tumor cell proliferation, DNA replication and colony formation." (PMID 39544949, 2024). "Differential expression analysis indicated a significant upregulation of the HMOX-1 gene in tumor prostate tissues compared to normal prostate tissues (P < 0.05)." (PMID 39091910, 2024). "More importantly, HMOX1 depletion greatly induced tumor cell growth and inhibited cell apoptosis and fer-1 protected UVM cells from apoptosis and necrosis induced by OE-HMOX1." (PMID 38767825, 2024). "In the control and HMOX1 knockdown groups, bortezomib reduced tumor diameter by 37.7% and 71.9% (fold change 1.91), respectively, and decreased tumor weight by 22.3% and 38.8% (fold change 1.72), respectively." (PMID 36775962, 2023). "Exposure of HCT116 tumor cells for 24 h to 64CuCl2 induced the upregulation of some hypoxia-responsive genes such as the HMOX1, MMP9, and VEGFA, the most striking overexpression being registered in the case of the HMOX1 gene." (PMID 37415761, 2023). "Consistently, the results of clonogenic assays revealed that HMOX1 or TGFB1 knockdown reduced the potential for colony formation by tumor cells." (PMID 37653101, 2023). "Our findings also align with previous observations linking HMOX1-expressing macrophages in the tumor microenvironment to cancer progression and unfavorable disease outcomes." (PMID 38060331, 2023). "To demonstrate the role of ERS-related genes in PDAC cells, we first analyzed the expression level in tumor and normal tissues of HMOX1 and TGFB1 using the TCGA, GSE41368 and GSE62165 datasets." (PMID 37653101, 2023). "Another consequence of HMOX1 dysregulation with an effect on the sensitivity of tumor cells to therapy is the modulation of drug transport." (PMID 37176114, 2023).
tumor (continued). "Heme oxygenase-1 silencing boosted Dox chemotherapy in the tumor cells and induced the polarization of macrophages in myeloid cells to activate immunotherapeutic activity." (PMID 37376208, 2023). "HCC tumor tissues contain high levels of HMOX1, S100A9, TMC7, TRAF3 and TRIM21, whereas the expression of IL8RAP and RGL4 were higher in the control group." (PMID 37171396, 2023). "Expression of HMOX1 pathway signature was elevated in RCC tissues compared with non‐tumor tissues (p < 0.001)." (PMID 37031459, 2023). "In this study, we found that pharmacological VC blocked the activation of the mTOR pathway and tumor growth by degrading Rictor and inducing HMOX1 expression." (PMID 36787291, 2023). "Meanwhile, in both HCT116 and HT29 colon tumor cells treated with [64Cu]CuCl2 an important fingerprint of hypoxia was registered through the upregulation of HMOX1, MMP9, and SERPINE1." (PMID 37415761, 2023). "Based on RT-qPCR results, miR-873-5p expression was lowered while HMOX1 expression was elevated in tumor tissues of GBM patients compared with normal tissues." (PMID 37382594, 2023). "Compared to that in peritumor tissues, the expression of ferroptosis-inducing genes, including PTGS2, ALOX12, TFR2, and HMOX1, was decreased in tumor tissues, whereas ferroptosis-suppressor genes, including SLC7A11 and GPX4, were increased." (PMID 37554285, 2023). "The antibody-loaded iLNPs induced heme oxygenase-1 silencing in tumor/myeloid cells, which led to different boosting effects." (PMID 37376208, 2023). "Found the HMOX1+ myeloid cells localized in the mesenchymal tumor area, which released IL-10 to drive T cell exhaustion." (PMID 36459212, 2023). "We also found that CINN-EO augmented the Fe(II) content within tumour cells and induced HMOX1 expression, suggesting that ferroptotic cancer cell death was activated." (PMID 36982774, 2023). "In summary, five of the genes (CARS1, CHAC1, FANCD2, G6PD, and HMOX1) in the prognostic model have been reported to contribute to ferroptosis and to be upregulated in BC tumor tissue, in contrast to AIFM2." (PMID 36313179, 2022). "HMOX1/OX1 is induced during oxidative stress by other drugs in tumor cells and mediates antioxidant and cytoprotective effects from ROS-induced cell death." (PMID 35955744, 2022). "HMOX-1 is elevated in a variety of human malignancies, indicating that it contributes to settle the tumor microenvironment for cancer cell growth, angiogenesis, and metastasis." (PMID 35422048, 2022). "While the role of HMOX1 in the colon remains to be thoroughly evaluated, studies show that HMOX1 can function as a tumor suppressor in CRC by inhibiting tumor invasion and metastasis." (PMID 36457077, 2022). "Shuganning induces ferroptosis via Heme oxygenase-1(HO-1) to increase intracellular iron accumulation and suppresses tumor growth in TNBC." (PMID 36467032, 2022). "The depletion of HMOX-1 using specific shRNA lentivirus particles inhibited cell and tumor proliferation in vitro and in vivo." (PMID 35053476, 2022). "The knockdown of Nrf2 expression inhibited the invasion capacity of tumor cell under hypoxic conditions and suppressed the expression of Nrf2, heme oxygenase-1 (HO-1) and HIF-1α." (PMID 35417854, 2022). "Elevated HMOX1 expression is found in a variety of tumors, supporting tumor cell survival, promoting proliferation and angiogenesis, as well as resisting apoptosis." (PMID 35370706, 2022). "The elevated expression of HMOX-1 in a variety of malignant tumors is related to the tumor microenvironment resistance to tumor cell growth, angiogenesis, metastasis, chemotherapy, and radiotherapy." (PMID 35069936, 2022).